RN7SL441P (RNA, 7SL, cytoplasmic 441, pseudogene)
Gene: Miscellaneous RNA gene on chromosome 12 (109,866,214 to 109,866,509, reverse strand). Ensembl gene ENSG00000241413.
Homologues: Orthologues: chimpanzee Metazoa_SRP (99% identical), macaque Metazoa_SRP (93% identical). Paralogues in human: RN7SL1 (84% identical), RN7SL2 (84% identical), RN7SL3 (83% identical), RN7SL296P (82% identical), RN7SL230P (81% identical), RN7SL680P (81% identical), RN7SL778P (81% identical), RN7SL186P (81% identical), RN7SL45P (81% identical), RN7SL589P (81% identical), RN7SL664P (81% identical), RN7SL679P (81% identical), and 702 more.